TET2 (tet methylcytosine dioxygenase 2)
Description:
Dioxygenase that catalyzes the conversion of the modified genomic base 5-methylcytosine (5mC) into 5-hydroxymethylcytosine (5hmC) and plays a key role in active DNA demethylation. Has a preference for 5-hydroxymethylcytosine in CpG motifs. Also mediates subsequent conversion of 5hmC into 5-formylcytosine (5fC), and conversion of 5fC to 5-carboxylcytosine (5caC). Conversion of 5mC into 5hmC, 5fC and 5caC probably constitutes the first step in cytosine demethylation. Methylation at the C5 position of cytosine bases is an epigenetic modification of the mammalian genome which plays an important role in transcriptional regulation. In addition to its role in DNA demethylation, also involved in the recruitment of the O-GlcNAc transferase OGT to CpG-rich transcription start sites of active genes, thereby promoting histone H2B GlcNAcylation by OGT.
Synonyms: KIAA1546; FLJ20032; IMD75; MDS
Tractability: Small molecule: a structure with a bound ligand is known; a high-quality ligand is known. PROTAC: UniProt records ubiquitination sites on it; ubiquitination databases record sites on it; a small molecule that binds it is known.
Target class: Enzyme; Oxidoreductase
Gene: Protein-coding gene on chromosome 4 (105,145,875 to 105,279,816, forward strand). Ensembl gene ENSG00000168769.
Subcellular location: Nucleus; Chromosome
Subcellular location (Human Protein Atlas): Nucleoplasm; Cytosol
Pathways (Reactome):
Gene expression (Transcription): TET1,2,3 and TDG demethylate DNA
Reproduction: Specification of primordial germ cells
Gene Ontology:
Molecular function: DNA 5-methylcytosine dioxygenase activity; ferrous iron binding; protein binding; zinc ion binding; 2-oxoglutarate-dependent dioxygenase activity
Biological process: leukocyte differentiation; myeloid cell differentiation; positive regulation of gene expression via chromosomal CpG island demethylation; positive regulation of transcription by RNA polymerase II; protein O-linked glycosylation; epigenetic regulation of gene expression; regulation of gene expression
Cellular component: chromosome; nucleoplasm; nucleus
Genetic constraint (gnomAD): Loss-of-function variants: 290 observed, 128.09 expected, observed/expected ratio (o/e) 2.26. Missense variants: 2,389 observed, 2,434.4 expected, observed/expected ratio (o/e) 0.98, 90% interval 0.95 to 1.01. Synonymous variants: 808 observed, 881.23 expected, observed/expected ratio (o/e) 0.92, 90% interval 0.87 to 0.97.
Gene-disease validity (ClinGen):
ClinGen rates the evidence that TET2 causes each of these diseases.
pulmonary arterial hypertension (autosomal dominant): Moderate. Pulmonary arterial hypertension (PAH) is a group of diseases characterized by mean pulmonary artery pressure >20 mmHg and elevated pulmonary arterial resistance leading to right heart failure.
Cancer hallmarks: invasion and metastasis (suppresses); invasion and metastasis (promotes); change of cellular energetics (promotes); genome instability and mutations (suppresses); suppression of growth (promotes); proliferative signalling (promotes); genome instability and mutations (promotes)
Homologues: Orthologues: chimpanzee TET2 (99% identical), macaque TET2 (97% identical), dog TET2 (86% identical), rabbit TET2 (82% identical), guinea pig TET2 (62% identical), rat Tet2 (61% identical), mouse Tet2 (59% identical), tropical clawed frog tet2 (46% identical), zebrafish tet2 (33% identical). Paralogues in human: TET3 (25% identical), TET1 (24% identical).
Diseases named in the same sentence as TET2 in open-access papers:
TET2 is named in the same sentence as 388 diseases in open-access papers, as found by Europe PMC text mining. Sharing a sentence is not in itself a finding about the gene and the disease. The quoted sentences say what the papers report.
leukemia (187 papers, 2011 to 2026). A malignant (clonal) hematologic disorder, involving hematopoietic stem cells and characterized by the presence of primitive or atypical myeloid or lymphoid cells in the bone marrow and the blood. "Current research highlights the connection between RA and increased leukemia risk, including shared epigenetic modifications such as ten-eleven translocation 2 (TET2) and DNA methyltransferase 3A (DNMT3A) mutations." (PMID 41141147, 2025). "In leukemia, TET2 loss-of-function mutations are associated with altered DNA methylation patterns and poor outcomes." (PMID 40646353, 2025). "Ascorbate supplementation increases TET activity in blood cells of ascorbate-deficient patients with leukemia or of TET2 germline mutation carriers, suggesting that ascorbate is also a physiological TET regulator in humans." (PMID 40213851, 2025). "Vitamin C has been shown to mimic TET2 restoration by enhancing tumor sensitivity to DNA damage and suppressing leukemia progression in TET2-deficient mouse hematopoietic stem and progenitor cells." (PMID 40141381, 2025). "TET2 mutations are considered early event in myeloid malignancies and additional mutations are needed for the development of full-blown leukemia." (PMID 38696033, 2024). "TET2, an enzyme facilitating mRNA demethylation, is implicated in regulating the migration and self-renewal of leukemia stem cells." (PMID 39164641, 2024). "Among older adults, clonal haematopoiesis driver genes, such as DNA methyltransferase 3A, tet methylcytosine dioxygenase 2, and additional sex combs like 1, are mutated the most frequently and are associated with all-cause mortality and risk of leukaemia." (PMID 39173170, 2024). "In patient-derived xenograft (PDX) models, STING inhibition specifically attenuates the proliferation of leukemia cells from TET2-mutated individuals." (PMID 37816954, 2023). "These clusters were significantly associated with leukemia burden, overall survival (OS), and 5hmC levels at the TET2 promoter." (PMID 37372359, 2023). "Consistent with their potential roles in CHIP, DNMT3A and TET2 mutations are early events occurring in HSCs during the clonal evolution to leukemia." (PMID 36675240, 2023). "Despite the epistatic relationship in the DNA methylation-hydroxymethylation pathway, DNMT3A and TET2 mutations are often concurrent in lymphoma and leukemia patients, suggesting that both enzymes sometimes work in parallel to produce a common result." (PMID 36675240, 2023). "CIMP in leukemia is associated with distinct molecular features, including TET2, IDH1 and IDH2 mutations in acute myeloid leukemia." (PMID 37234978, 2023). "TET2 is a key regulator of HSCs homeostasis, and somatic mutations in the TET2 gene can occur with both leukemia and MDS." (PMID 37038215, 2023). "NPM1 mutations correlate with most mature stages of leukemia arrest together with TET2 or IDH mutations in granulocyte progenitors-like AML or with DNMT3A mutations in monocyte progenitors-like AML." (PMID 35973983, 2022). "Combined loss of Tet2/3 in adult HSCs blocks differentiation and promotes aggressive leukemias causing rapid death of mice." (PMID 35235365, 2022). "One of the most frequent alterations that appear to initiate this deregulation and persist in leukemia patients are mutations in epigenetic regulators such as TET2." (PMID 35159097, 2022). "Vitamin C-induced genome DNA hypomethylation was also observed in human leukemia cell lines and was associated with increased TET2 activity." (PMID 35269864, 2022). "Previous studies have found that TET2 mutations are an extremely common type of mutation in leukaemia." (PMID 36684288, 2022). "Similar to IDH1/2 mutations, mutations in and the promoter hypermethylation of TET2 have been confirmed in leukaemias, myelodysplastic syndrome, myeloproliferative neoplasms and low-grade diffuse gliomas." (PMID 34905094, 2022).
leukemia (continued). "Mutations in IDH1/2 and the epigenetic silencing of TET2 occur in leukaemia or glioma in a mutually exclusive manner." (PMID 34905094, 2022). "In patients with leukaemia, the most common point mutations of human TET2 lead to disruption of its catalytic activity and are grouped within well-structured parts of the catalytic domain, on its surface." (PMID 35382873, 2022). "This is further supported by evidence that TET2-deficient leukemia cells rely on residual TET activity coming from TET1 and TET3 for their proliferative advantage and survival." (PMID 35085104, 2022). "In this line, Cimmino and colleagues, showed that treatment with vitamin C mimics TET2 restoration in Tet2-deficient mouse HSPCs, suppressing human leukemic colony formation, and leukemia progression in primary human leukemia patient-derived xenografts (PDXs)." (PMID 35832559, 2022). "Overexpression of TET1 or TET2 can cause a global decrease in 5-mC, and mutation affecting the TET2 enzyme are critical in tumor development and particularly in leukemia." (PMID 35327559, 2022). "In this context, treatment with vitamin C induces TET2 restoration in TET2-deficient mouse hematopoietic progenitors and is able to suppress leukemia progression." (PMID 34440317, 2021). "Taken together, our in vivo results indicate that the loss of p300 in the context of monoallelic or biallelic loss of Tet2 accelerated disease progression and the onset of leukemia." (PMID 34622806, 2021). "In blast cells of leukemia patients with TET2 mutations, aberrant promoter methylation and reduction in 5hmC at the level of gene enhancers were detected." (PMID 33804775, 2021). "Mechanistically, the loss of p300 in Tet2-deficient HSPCs altered enhancer accessibility and the expression of genes associated with differentiation, proliferation, and leukemia development." (PMID 34622806, 2021). "TET1 is an MLL partner in cases of acute myeloid (AML) and lymphoid (ALL) leukemias, while loss of function of TET2 is strongly associated with myelodysplastic syndromes, myeloproliferative neoplasms, and myeloid leukemias." (PMID 33520997, 2020). "Enhancing the activity of TET proteins with vitamin C can protect hematopoietic stem cells that have Tet2 mutations from aberrant proliferation in vitro and leukemia progression in vivo." (PMID 33520997, 2020). "TET2 mutations have also been described as leukemia-associated events that appear to be present in up to 25% of patients with myeloid neoplasm." (PMID 32748835, 2020). "Although loss of 5-hmC has been observed in various cancers, TET2 mutations are only frequently detected in leukemia." (PMID 33097695, 2020). "As a result, IDH1/2 mutations promote leukemia development by interfering myeloid differentiation and aberrantly enhancing c-Kit expression through the disruption of TET2-mediated DNA demethylation." (PMID 31527484, 2019). "As the majority of these hypermethylated enhancers are associated with tumor suppressor genes, it thus proposes an epigenetic mechanism that is associated with TET2 mutations in leukemia development." (PMID 31527484, 2019). "Cumulatively, these data suggest that ascorbate is able to mitigate the effect of Tet2 loss in models of leukemia at least in part by upregulating TET2 activity." (PMID 30018566, 2018). "In humans and L-gulonolactone oxidase mutant mice studies, ascorbate promoted TET2-dependent 5hmC formation allowing normal differentiation while ascorbate or TET2 deficiency allows HSCs to proliferate resulting in leukaemia." (PMID 29567393, 2018). "In fact, several leukemia and lymphoma disorders have a TET2 that is mutated at notably high frequencies (chronic myelomonocytic leukemia: 35–50%; AITL: 50–80%; PTCL-NOS: 40–50%)." (PMID 28505169, 2017). "Missense mutations in Ten-eleven translocation 2 (TET2) gene are frequently found in leukaemia patients." (PMID 28130413, 2017). "Recent studies reveal that TET2 mutations occur throughout the CDS of TET2 in various leukaemia patients." (PMID 28130413, 2017).
leukemia (continued). "In cancer, the global loss of 5hmC has been frequently associated with TET2 somatic mutations in leukemia or with TET1 silencing in solid tumors." (PMID 27587280, 2016). "Studies using a large cohort of leukemia patients suggest frequent TET2 mutations in myeloid malignancies and B- and T-cell lymphoma." (PMID 26861406, 2016). "TET2 has been implicated in leukemia and associated with decreased overall survival in AML, as its loss of function was found to impair differentiation and favor myeloid tumorigenesis." (PMID 27385100, 2016). "Recent studies have pointed out the causal role of IDH1 mutations in Glioblastoma-CIMP and tight associations between IDH2 and TET2 mutations with other CIMPs (leukemia, enchondroma, and spindle cell hemangioma)." (PMID 26463173, 2015). "Loss-of-function mutations in the demethylating enzyme TET2 have been previously associated to CIMP in leukemia, and our results reveal recurrence of this mutation in CIMP+ for other types such as UCEC and READ." (PMID 25960768, 2015). "Utilizing patient samples and in vivo modeling, we establish that leukemia-initiating clones driven by TET2 mutations can emerge independently of JAK2-mutant cells and undergo positive selection in the pro-inflammatory MPN environment, leading to parallel disease evolution." (PMID 41333431, 2025). "We observe that age is highly connected to the mutations SF3B1, SRSF2, and TET2, and the chromosomal abnormality -5/del(5q), which may reflect leukemias deriving from previous MDS clones, resulting as an accumulation of genetic driver events later with age." (PMID 40301336, 2025). "Moreover, reversing TET2 deficiency suppresses the abnormal differentiation and self-renewal of hematopoietic stem and progenitor cells and blocks leukemia progression." (PMID 40459008, 2025). "Overall, this experimental study demonstrated for the first time that the NSUN2-TET2-MBD6-BAP1/PR-DUB axis in human leukaemias (and most likely in other malignancies as well) is the key underlying mechanism for leukaemogenesis and carcinogenesis in TET2-depleted cells." (PMID 39757230, 2025). "Co-occurrence of TET2 mutations with FLT3-ITD mutations may result in the development of leukemia inducing synergistic gain-of-function effects on DNA methylation, therefore gene expression." (PMID 38696033, 2024). "However, unlike aggressive AML models induced by for example KMT2A fusion genes, Tet2-deficient mice showed a long latency before developing leukemia." (PMID 37816954, 2023). "In the context of leukemia with TET2 mutations, it has been recently shown that supplementation with Vitamin C - a co-factor of the TET2 enzyme - can rescue the function of wildtype TET2 and restore normal DNA methylation." (PMID 37601659, 2023). "In light of these findings, we asked whether elevated CEBPA level and not the CEBPA mutation(s) per se, drives the selective pressure for GATA2 and/or TET2 loss in AML to achieve moderate GATA2 levels that are optimal for leukemia growth." (PMID 37794021, 2023). "The leukemias were transplantable into secondary recipients, and the shorter latency of the TET2-deficient CebpaDM AML was preserved in this setting, indicating that TET2 not only has important tumor suppressive functions during malignant transformation but also during progression of AML." (PMID 37794021, 2023). "Furthermore, the presence of additional internal tandem duplications (ITDs) in the juxtamembrane domain of FLT3 cooperated with ascorbate deprivation in acceleration of leukemia development, phenocopying TET2 loss." (PMID 35938170, 2022).
leukemia (continued). "Vitamin C treatment was also tested in murine IDH1 mutant leukemic cells, showing TET2-dependent 5-hmC gain, 5-mC loss, and upregulation of gene expression that correlates with decreased self-renewal of leukemia stem cells and increased differentiation towards the mature marrow phenotype." (PMID 35269864, 2022). "In the non-malignant samples, TET2, ASXL1, PDS5B, NUP214, and SMC1A were recurrently mutated underlining that some variants may occur as early events (e.g., TET2) providing growth advantage possibly leading to overt leukemia." (PMID 35884491, 2022). "In murine models of leukemia, administration of vitamin C has been shown to restore TET2 function, resulting in an increase in 5-mC formation, global DNA hypomethylation, self-renewal block, and inhibition of disease progression in TET2-deficient mice." (PMID 35269864, 2022). "In these models, TET2 loss of function is associated with DNA hypermethylation at regulatory regions of lineage and differentiation genes whose deregulation in a TET2-deficient context is consistent with the transformed phenotype of these leukemia." (PMID 35393954, 2022). "Severe deficiency of both Tet2 and Tet3, is associated with >90% loss of 5hmC in HSPCs and causes the spontaneous accumulation of DSBs, marked by elevated and persistent yH2AX foci and rapid leukemia progression." (PMID 34017357, 2021). "Studies have shown that leukemia-associated missense mutations impair the enzymatic activity of TET2 and lead to a decrease in the genomic level of 5-hydroxymethyl-cytosine, which disrupts normal hematopoiesis and may accelerate leukemia formation." (PMID 30984620, 2019). "TET1, an ortholog of TET2, catalyses the conversion of 5-methylcytosine (5mC) in DNA to 5-hydroxymethylcytosine (hmC), which suggests that epigenetic regulation plays a critical role in leukaemia development caused by TET2 mutations." (PMID 28130413, 2017). "Thus, loss of 5hmC expression is expected in tumours harbouring mutations in IDH, FH, SDH, similar to leukemias with mutations in TET2." (PMID 28484589, 2017). "The discovery of their direct interaction via the CR domain sheds new light on the connection between DNA hydroxylation and histone methylation, and its impact on chromatin and DNA biology, the pathogenic mechanisms of TET2-mutated leukaemia, and the epigenetic mechanisms in which they participate." (PMID 28130413, 2017). "Notably, TET2 has been already associated with breast cancer at the RNA level and it is considered a known somatic driver in leukemia and melanoma." (PMID 28569218, 2017). "Leukemia-associated TET2 mutations cause loss of function with respect to TET2-mediated hydroxymethylation, leading to increased cytosine methylation in patients with TET2 mutations." (PMID 27835592, 2016). "Importantly, reduced 5hmC does not always correlate with presence of IDH mutation and IDH mutations are largely mutually exclusive to TET2 mutations in leukaemia." (PMID 25853800, 2015). "Thus, it is apparent that TET2 mutations interrupt normal DNA hydroxymethylation and have an as yet uncertain role in the development of leukemia." (PMID 24778653, 2014). "Furthermore, compared to the DMSO group, the proliferation of TET2-mutated leukemia cells was significantly reduced in the BM of recipient mice treated with H-151, and no inhibitory effect was observed in the recipients of leukemia cells harboring wildtype TET2." (PMID 37816954, 2023). "Interestingly, mutations in the CRD of Tet2 have been found in leukemia patients." (PMID 36056023, 2022).